RN7SL43P (RNA, 7SL, cytoplasmic 43, pseudogene)
Gene: Miscellaneous RNA gene on chromosome 7 (66,980,120 to 66,980,410, forward strand). Ensembl gene ENSG00000275878.
Homologues: Orthologues: chimpanzee Metazoa_SRP (98% identical), macaque Metazoa_SRP (81% identical), guinea pig Metazoa_SRP (79% identical). Paralogues in human: RN7SL625P (96% identical), RN7SL1 (87% identical), RN7SL2 (87% identical), RN7SL3 (87% identical), RN7SL126P (84% identical), RN7SL220P (84% identical), RN7SL769P (84% identical), RN7SL219P (82% identical), RN7SL397P (82% identical), RN7SL664P (82% identical), RN7SL45P (82% identical), RN7SL652P (82% identical), and 703 more.